GPC3 (glypican 3)
Diseases named in the same sentence as GPC3 in open-access papers (continued):
Sharing a sentence is not in itself a finding about the gene and the disease.
hepatocellular carcinoma (continued). "Unlike GPC3 CAR-T cells, CD133 CAR-T cells not only block the nutritional supply to tumor cells but also are used in combination with other drugs to treat hepatocellular carcinoma." (PMID 39136031, 2024). "Notably, there was a distinctive positive correlation between the plasma GPC3 level in hepatocellular carcinoma patients and the concentration of IGF-1R which means targeting of GPC3/IGF-1 axis could be used to treat HCC." (PMID 37305177, 2023). "Many previous studies have shown that single anti-GPC3 treatments, including utilization of GC33 or HN3 antibody were not sufficient for elimination of hepatocellular carcinoma." (PMID 32127929, 2020). "Although no clinical CAR T-cell trials for hepatocellular cancer have been completed to date, some preclinical and clinical evidence suggests a potent antitumor activity for therapies targeting CEA, MUC-1, and GPC-3 antigens." (PMID 31936611, 2020). "Glypican-3, heat shock protein 70, and glutamine synthetase (GS) are markers currently used, as a single panel, to discriminate the nature of a <2 cm hepatocellular lesion lacking radiological features of hepatocellular carcinoma (HCC) detected in a cirrhotic patient under surveillance." (PMID 28280721, 2017). "Specific role of GPC3 in cancer and inflammatory disease at different times seems to have a clear and reasonable disease control, e.g., severe pneumonia with or without ARDS, or virus-infected patients with hepatocellular carcinoma compared with other liver diseases." (PMID 28510121, 2017).
liver cancer (135 papers, 2012 to 2026). An epithelial or non-epithelial malignant neoplasm that arises from the liver. "Several tumors, particularly liver cancer, express high levels of Glypican-3 (GPC-3), a marker associated with poor prognosis." (PMID 39404428, 2024). "For the 42A1 antibody, which targets the liver cancer antigen glypican-3, the variant T57H in the second complementarity-determining region of the heavy chain (CDR-H2) exhibited a 2.6-fold improvement in affinity, as well as enhanced cell-binding activity." (PMID 35545451, 2022). "GPC3 is specifically associated with liver cancer and, although it is useful in HCC diagnosis, an individual marker is not able to meet the needs of clinical therapeutic application." (PMID 35251989, 2022). "The N-leaf cysteine-rich domain (CRD) of GPC3 has a Wnt-binding groove, and the mutation of the notch reduces binding, thereby reducing Wnt activation, and inhibiting the growth of mouse liver cancer." (PMID 35251989, 2022). "Although GPC3 as a specific marker of liver cancer has been studied widely, the diagnostic capacity of serological GPC3 for HCC is controversial." (PMID 33817137, 2019). "The unique expression profile of GPC3 and its association with signaling pathways make it a potential therapeutic target for the treatment of liver cancer." (PMID 27669301, 2016). "Furthermore, CTNNB1 mutations play a broader role in liver cancer by activating the Wnt/β-catenin pathway, which is further influenced by the overexpression of Glypican 3 (GPC3)." (PMID 39684755, 2024). "Therefore, the CD107a (lysosomal-associated membrane protein-1)-mediated externalization of GPC3 peptide-specific CTL clones was examined upon exposure to liver cancer cell lines." (PMID 25354479, 2015). "To allow the identification of liver cancer patients that express GPC3, and to visualize the tumor size and locations, we developed a new diagnostic imaging probe by conjugating the standard magnetic resonance imaging (MRI) contrast agent to a highly specific chimeric anti-GPC3 antibody." (PMID 41154412, 2025). "Also, GPC3 located on the surface of liver cells, so that antibody-based drugs or CAR-T/NK can be designed for specific killing of tumor cells with low risk of off-tumor effect.All these features determine GPC3 is the best diagnostic and therapeutic target for liver cancer." (PMID 32127929, 2020). "Here, we report a chemically assembled macrophage-engaging glypican-3 × signal regulatory protein-α (SIRP-α) bispecific antibody for the treatment of liver cancer." (PMID 42318525, 2026). "Here, we demonstrate that GPC3 expression confers radioresistance in liver cancer through integrated in vitro, in vivo, and patient-level clinical analyses." (PMID 42182336, 2026). "Together, these findings identify GPC3 as a determinant of radioresistance in liver cancer and suggest its potential utility as a biomarker to guide radiotherapeutic strategies." (PMID 42182336, 2026). "Following 14 weeks of NDEA exposure,the development of the liver cancer model was validated through assessmentof serum glypican-3, an early serum marker for liver cancer." (PMID 41078144, 2025). "IL21-armed CAR-T has been used in a clinical trial targeting several solid tumors expressing GPC3 antigen, including Liver Cancer, Rhabdomyosacoma, Malignant Rhabdoid Tumor, Liposarcoma, Wilms Tumor, and Yolk Sac Tumor (NCT04715191), but not ESCC." (PMID 40722671, 2025). "Ongoing exploration of novel or optimized targets includes B7-H3 and GD2 for brain cancer, MSLN and CEA for pancreatic cancer, MSLN and FAP for mesothelioma, and GPC3 for liver cancer." (PMID 40969260, 2025). "A volcano plot identified glypican-3 (GPC3) as one of the most significant DEGs in the Liver ECM group, a key molecular marker associated with aggressive liver cancer and widely used for its diagnosis." (PMID 40852642, 2025).
liver cancer (continued). "At present, GPC3 has been extensively studied in this family, and elevated serum GPC3 can serve as a potential biomarker for predicting early liver cancer." (PMID 39823268, 2025). "We also find increased expression of myofibroblasts and fibrosis markers (PDGFRB, COL1A1, COL3A1, COL11A1) and early liver cancer markers (GPC3 and MUC1)." (PMID 41065540, 2025). "The up-regulated expression of GPC3 in liver cancer, along with its pro-oncogenic properties, has been explored intensively and extensively." (PMID 40422229, 2025). "In liver cancer cell lines and animal models, our GPC3-based MRI probe selectively identified GPC3-positive tumors with good clarity and low side effects." (PMID 41154412, 2025). "Modulating GPC3 gene expression can induce liver cancer cell death by disrupting growth factor signaling, cell adhesion, and metabolic regulation." (PMID 40657181, 2025). "The animalsdemonstrating a 2-fold or more increase in GPC-3 levels relative toControl animals were considered positive for liver cancer and dividedinto Tumor and Tumor + AG-AuNPs groups." (PMID 41078144, 2025). "Recently, Chen130 constructed GPC3-CAR-NK cells based on an affinity-enhanced antibody targeting GPC3 for the treatment of liver cancer patients." (PMID 38245520, 2024). "This linker has two main functions: it connects to the nanoparticles through a chitin-binding domain, and it targets liver cancer cells that express a specific protein, glypican-3 (GPC3)." (PMID 38792650, 2024). "A curated panel of 30 LRIs specific to liver cancer was formulated, several of which have known associations with LC, including noteworthy ligands like SERPINC1, GPC3, and receptors such as ERBB3." (PMID 39850635, 2024). "When injected into a patient, the GIP1 part of the linker specifically binds to GPC3 on the liver cancer cells." (PMID 38792650, 2024). "Alpha-fetoprotein (AFP), Osteopontin (OPN) and Glypican-3 (GPC-3) are commonly used as tumor markers for primary liver cancer." (PMID 37575092, 2023). "Differential expression of Glypican-3 (GPC-3) is observed throughout the invasive phase of liver cancer growth, suggesting a role for its expression in the etiology and progression of this disease." (PMID 36850982, 2023). "Previous studies have also shown that extracellular PKCδ activates IGF1R signaling involved in GPC3-expressing liver cancer cell lines such as HepG2 and HuH7." (PMID 37241771, 2023). "Normally, GPC3 appears in liver cancer and fetal liver, whereas ALB is specifically expressed in the adult liver." (PMID 37017469, 2023). "GPC-3 is overexpressed in liver cancer tissues, and only a small amount is expressed in healthy liver tissues." (PMID 37920165, 2023). "HN3 refers a human antibody, which was reported to have excellent affinity to overexpressed GPC3 protein on the surface of liver cancer cells in several CAR-T studies." (PMID 37202772, 2023). "This CAR not only used the SynNotch receptor as a switch for tumor antigen recognition, but also had dual-target recognition specificity for GPC3 and CD147, which further limited CAR to selectively recognize GPC3+CD147+ liver cancer cells." (PMID 36761757, 2023). "The mcherry red fluorescent tag was integrated to GPC3+ Huh7 liver cancer cells via lenti-virus transduction and turn to be CPC3+ mcherry expressing Huh-7 cells." (PMID 37202772, 2023). "A recent study revealed that inhibition of GPC-3 cleavage results in reduced cell proliferation in liver cancer cell lines, which is also confirmed by our observations." (PMID 37446098, 2023). "Combination of PD-L1 CAR (B2) T cells with CAR T cells targeted by GPC3 (a liver cancer-specific antigen) regresses liver tumors in mice." (PMID 35317524, 2022). "Based on our previous investigation, the expression of miR-4510 was correlated with GPC3 in liver cancer." (PMID 35050429, 2022).
liver cancer (continued). "Strong GPC3 fluorescence signal intensity (green) was visible on the surface of human liver cancer Hep-G2 cell membrane and in the intercellular space, but the intensity of ARG1 (yellow) signal was comparatively low." (PMID 35331259, 2022). "In order to evaluate the therapeutic potential of Ad-GPC3 vaccine and IL-12 co-immunization in preventing tumor metastasis in the animal model, we established a model of lung metastasis of liver cancer in mice." (PMID 36139670, 2022). "Our work demonstrated that, due to high affinity, excellent thermostability and potency, chicken mAbs targeting the N-lobe of GPC3 are appealing candidates to develop potent ADCs for immunotherapy of liver cancer." (PMID 35281879, 2022). "We examined blood samples from HBL patients with active β-catenin-TCF4 pathways in primary liver cancer and discovered GPC3 and AFP in their bloodstream." (PMID 36551548, 2022). "Glypican-3 and arginase-1 are among the most effective diagnostic markers for HCC, the positive staining thus confirming the liver cancer identity of the transformed iHeps." (PMID 34302118, 2021). "In order to overcome this defect, experts have developed a corresponding antibody-specific anti-GPC3 monoclonal (Anti-GPC3 Ab) through the relatively specific expression molecule glypican-3 (GPC3) of liver cancer." (PMID 34923912, 2021). "GPC3 has been the target of molecular imaging for early liver cancer, especially the positron emission tomography imaging technology for GPC3 has matured nowadays." (PMID 34200243, 2021). "Our probe consists of the 89Zr radioisotope conjugated to a humanized monoclonal antibody against glypican-3, and it demonstrates specific ability to detect patient-derived liver cancer xenografts in a mouse model." (PMID 34439132, 2021). "More importantly, research has revealed that GPC3 levels are increased not only in liver cancer tissues, but also in serum." (PMID 34200243, 2021). "The results of the research showed that GPC3 was widely positively distributed in the cytoplasm and cell membrane of liver cancer cells." (PMID 34923912, 2021). "First, the expression levels of liver cancer-associated markers, AFP, GPC3 and CK19 as well as liver CSC markers, CD44, CD24 and CD133, in malignant tumours were relatively high compared to that in normal liver by RT-qPCR." (PMID 32203212, 2020). "Here, we synthesized and evaluated the efficacy of [225Ac]Ac–Macropa–GC33 in mice engrafted with the GPC3-expressing human liver cancer cell line HepG2." (PMID 33374953, 2020). "It was reported that many chemotherapeutic agents which has been used for treatment of hepatic cancer have binding affinity to GPC-3 protein." (PMID 33126630, 2020). "Using flow cytometry, we further confirmed the expression of liver cancer-associated markers such as AFP, GPC3 and carcinoembryonic antigen (CEA) in miPS-Huh7cmP1 cells in comparison with Nanog." (PMID 32203212, 2020). "A large number of studies have shown that GPC3 is more sensitive than AFP in the diagnosis of liver cancer." (PMID 32127929, 2020). "Studies have shown that GPC3 can help the activation of WNT signaling by promoting the formation of membrane surface complexes in liver cancer." (PMID 32127929, 2020). "Glypican-3(GPC3) is a transmembrane protein which has been found to be frequently overexpressed on the surfaces of liver cancer (LC) cells, which contributes to both the growth and metastasis of LC cells." (PMID 31781603, 2019). "The GPC-3-expressing T-cells have been tested for anti-tumor effects in pediatric liver cancers (NCT02932956) in combination with chemotherapy." (PMID 31769427, 2019). "By attracting and storing growth factors via HS chains and recognizing Wnt as a co-receptor, GPC3 acts as a cell surface glycoprotein that can modulate Wnt signaling in liver cancer." (PMID 31428581, 2019).
liver cancer (continued). "In a third AEGIS-Cell-SELEX experiment, cell engineering was used to place glypican 3 (GPC3), a possible marker for liver cancer diagnostic, on the surface of a murine cell line that does not express GPC3 (1MEA)." (PMID 29747381, 2018). "A study concerned with imaging in liver cancer placed emphasis on a proteoglycan known as glypican-3 (GPC-3), which is involved with enabling cell growth and is found to be overexpressed in HCC." (PMID 29772748, 2018). "Glypican-3 (GPC3) is highly expressed in HCC and has been established as a histochemical diagnostic marker for liver cancer." (PMID 27419635, 2017). "Here, we report the decrease of 5 new GPC3-regulating miRNAs in two independent cohorts of liver cancer tissues." (PMID 28476031, 2017). "Here we constructed two mPE24-based immunotoxins against GPC3 and tested their ability to treat liver cancer in cellular and mouse models." (PMID 27419635, 2017). "Because miR-4510 inhibits liver cancer cell proliferation through GPC3, which is involved in Wnt/β-catenin pathway activation, we investigated miR-4510 effect on this pathway." (PMID 28476031, 2017). "Altogether these data demonstrate that miR-4510 is a powerful antitumoral agent in liver cancer and acts in part through GPC3 downregulation." (PMID 28476031, 2017). "Previous studies have shown that GPC3-CAR T cells efficiently eradicate liver cancer cells lines that possess a high level of GPC3 expression in vivo." (PMID 28123387, 2016). "This study successfully humanizes and validates high affinity anti-GPC3 antibodies and sets a foundation for future development of these antibodies in various clinical formats in the treatment of liver cancer." (PMID 27667400, 2016). "Altogether, these observations suggest that the HS chains on GPC3 are involved in HGF/Met activation in liver cancer cells." (PMID 26332121, 2015). "In conclusion, we reported the role that the HS chains of GPC3 play in liver cancer cell migration and motility." (PMID 26332121, 2015). "It was also demonstrated that blocking PD-1 increased the number of GPC3-specific CTL clones that degranulate against these liver cancer cell lines in vitro." (PMID 25354479, 2015). "On the other hand, some other studies reported that endogenous GPC3 inhibited the cell proliferation of liver cancer cells." (PMID 22606345, 2012). "Owing to the high expression of GPC3 in liver cancer stem cells, additional functional studies were performed to investigate if GPC3 has pivotal roles in regulating the growth of liver cancer stem cells." (PMID 22606345, 2012). "Similarly, the CAR-T drug C-CAR031 (CTR20243113, NCT05155189), targeting GPC3, has demonstrated good safety and significant antitumor activity in liver cancer patients, with 14/24 patients achieved objective response and 91.3% disease controlled." (PMID 41014398, 2025). "In liver cancer, glypican-3 (GPC3) has emerged as a key target for CAR-NK therapy in HCC." (PMID 40260240, 2025). "This probe may help identify liver cancer patients suitable for GPC3-targeted therapies and monitor their treatment response in a safe and non-invasive manner." (PMID 41154412, 2025). "GPC-3 is an excellent serum marker that appears quite early in the development of hepatic cancer." (PMID 38990437, 2025). "Anti-GPC3's role was to guide NPs toward GPC3-overexpressing HepG2 liver cancer cells." (PMID 40880603, 2025). "A large percentage of liver cancer patients express a protein called glypican-3 (GPC3)." (PMID 41154412, 2025). "Recently, CD147 has emerged alongside GPC3 as a promising therapeutic target in liver cancer." (PMID 41465318, 2025). "Common targets in liver cancer include GPC3, AFP, hepatocyte growth factor receptor, and MUC1." (PMID 40242773, 2025). "Importantly, with this strategy, 92.5% of HepG2 cells were DAPI+; of those, 100% were ICG+; and, of those, 98.6% were GPC3+, showing the specificity and sensitivity of the panel for identifying liver cancer cells." (PMID 38727682, 2024).